MCL1 (MCL1 apoptosis regulator, BCL2 family member)
Diseases named in the same sentence as MCL1 in open-access papers (continued):
Sharing a sentence is not in itself a finding about the gene and the disease.
melanoma (continued). "Notably, gene expression analysis of the ARF-deficient and INK4a-deficient melanomas arising in our HGF/SF transgenic mice also identified MCL-1 as one of the top overexpressed genes associated with more malignant melanomas." (PMID 27846237, 2016). "Suberic bishydroxamate induces apoptosis in melanoma cells by the upregulation of Bim, Bax, Bak, while down regulating the expression of anti-apoptotic X-linked inhibitor of apoptosis, B-cell lymphoma-extra-large (Bcl-xL) and myeloid cell leukemia 1 (Mcl-1)." (PMID 25738536, 2015). "Finally, treatment of melanoma cells with a combination of vemurafenib or dabrafenib with trametinib also caused remarkable induction of Mcl-1 which was more as compared to individual treatments." (PMID 26497853, 2015). "Additionally, our previous studies on tissue sections have shown that Mcl-1 and Bcl-XL expression is associated with progression of melanoma, whereas Bcl-2 levels decrease during progression of melanoma." (PMID 24367627, 2013). "Therefore, sensitivity to the combination of MCL1 + AZA may be similarly associated with mutational status in melanoma." (PMID 34451846, 2021). "Therefore, presented in our study apoptosis induction in amelanotic melanoma cells may be also associated with the displace Bim from Mcl-1." (PMID 31432325, 2020). "We utilized gene and microRNA (miRNA) expression data from INK4a- and ARF-associated melanoma models, as well as available human melanoma databases, to uncover an important role for a pathway centered on the tumor suppressor miRNA miR-32 and the anti-apoptosis oncogene MCL-1." (PMID 27846237, 2016). "In multiple myeloma and melanoma, MCL1 inhibitors like S63845 combined with HDAC inhibitors or redox modulators upregulate pro-apoptotic proteins like BIM and NOXA, resensitizing resistant cells." (PMID 41155156, 2025). "Blocking STAT3 or SRC signaling decreases key cell survival proteins, including Bcl-xL and Mcl-1 (Myeloid cell leukemia-1), precipitating apoptosis in melanoma cells." (PMID 40399946, 2025). "In the case of melanoma cells, an increase in the expression of antiapoptotic proteins, including the Mcl-1 protein (Myeloid Cell Leukemia 1), is often observed." (PMID 40807447, 2025). "Direct co-targeting of Bcl-xL and Mcl-1 in cervical cancer, melanoma, and medulloblastoma has been shown to synergistically reduce cell viability." (PMID 40704654, 2025). "Treating melanoma cells with Thio induces apoptotic death that is inversely correlated with the antiapoptotic Mcl-1 expression level." (PMID 40628925, 2025). "For example, BCLXL and MCL1 are critical for cell survival in melanoma, rendering them inherently resistant to BCL2 inhibitors alone." (PMID 41155156, 2025). "NSG mice were inoculated with melanoma cells transduced with control or doxycycline-inducible shRNA against MCL1 either alone or with HK2 overexpressing vector." (PMID 41326406, 2025). "Similar to the results obtained in melanoma, depletion of MCL1 in AML cells (MV4-11 and MOLM13) led to suppression of mTORC1 activity." (PMID 41326406, 2025). "Herein, for the first time, we have demonstrated that MXFL and MIM1—the Mcl-1 protein inhibitor used in the two-component model exert high cytotoxic and proapoptotic activity towards A375 and G361 melanoma cells." (PMID 40807447, 2025). "Treatment of melanoma cells with two specific and potent MCL1 inhibitors ABBV-46771 and UMI-7735,72,73, resulted in inhibition of mTORC1 in dose- and time- dependent manner." (PMID 41326406, 2025). "We report, for the first time, the high proapoptotic activity of MIM1 and MXFL applied in a two-component model toward melanoma cells, pointing to the Mcl-1 protein as an important molecular target." (PMID 40807447, 2025). "PLX4720-mediated apoptosis resistance via upregulated Mcl-1 was accompanied by highly invasive properties in NRAS-mutant melanoma cells." (PMID 39935431, 2025).
melanoma (continued). "Mcl-1 and Bcl-xL have also been identified as critical for melanoma cell survival and therapy resistance." (PMID 38542429, 2024). "It justifies the further development of next generation MCL1 inhibitors to improve efficacy of ICIs in treating malignant melanoma." (PMID 38459020, 2024). "In melanoma cells, Mcl-1 and Bcl-xL have been suggested as critical for melanoma cell survival, based on reduced cell viability and induced apoptosis when S63845 was combined with ABT-263 or ABT-199." (PMID 38542429, 2024). "Mcl-1 is well known as a critical survival factor for diverse cell death stimuli in many tumor cells, including non-small cell lung cancer and melanoma cells." (PMID 38200153, 2024). "Uveal and mucosal melanoma cell lines have been shown to be more sensitive to the MCL1 inhibitors than cutaneous melanomas through the inhibitor’s direct killing effects." (PMID 38459020, 2024). "This study aims to explore the therapeutic potential of MCL1 inhibitors to target MDSCs and improve the efficacy of ICIs for melanoma." (PMID 38459020, 2024). "Together, this proof-of-concept study demonstrates the potential of combining an MCL1 inhibitor with anti-PD-1 in the treatment of melanoma." (PMID 38459020, 2024). "It is clear that Mcl-1 downregulation can sensitize melanoma cells for apoptosis, as seen also by siRNA strategies." (PMID 38542429, 2024). "While the effects on ROS in response to the inhibitor combinations used here had not previously been investigated, some increase in ROS levels has been reported in melanoma cells in response to the Mcl-1/Bcl-xL/Bcl-2-selective BH3 mimetic TW-37." (PMID 38542429, 2024). "We further confirmed the expression of MCL1 in MDSCs from other 10 melanoma tumors using flow cytometry." (PMID 38459020, 2024). "In recent years, there has been a growing interest in the use of MCL1 inhibitors to treat solid tumors including melanoma." (PMID 38459020, 2024). "Combination therapy targeting MCL-1 and Bcl-xL effectively eliminates melanoma cells from patients who experience relapse after PD-1 or CTLA-4 remedy, and curtails the self-renewal capability of melanoma cells." (PMID 39403382, 2024). "Loss of mitochondrial membrane potential was found in A-375 melanoma cells in response to the BH3 mimetic gossypol, as well as in response to the Mcl-1 antagonist obatoclax in combination with tunicamycin." (PMID 38542429, 2024). "This study is the first to report the antitumor immunomodulatory effects of the MCL1 inhibitor S64315 in melanoma." (PMID 38459020, 2024). "Downregulation of Mcl-1 or Bcl-2 in response to vemurafenib has also previously been reported in melanoma cells." (PMID 36902392, 2023). "Consistent with these in vitro data, CD47 mRNA expression in TCGA melanomas had highly significant positive correlations with MCL1, CD40LG, TIGIT, and TNF mRNA expression." (PMID 36768931, 2023). "As MCL-1 is crucial for melanoma survival, we investigated its expression in trametinib-resistant cells during alternating periods of trametinib withdrawal and rechallenge." (PMID 37835493, 2023). "In another study, it has been demonstrated that trametinib was synthetic lethal with the MCL-1 inhibitor AZD5991 by promoting apoptosis of melanoma cells and inhibiting the growth of patient-derived xenografts." (PMID 37835493, 2023). "In melanoma cells, enhanced caspase-3 activation and mitochondrial activation have been reported in response to combinations of S63845 or TW-37 (targeting Mcl-1, Bcl-xL and Bcl-2) with BRAF inhibitors (vemurafenib or encorafenib)." (PMID 36902392, 2023).
melanoma (continued). "Based on their strong positive correlations with CD47 mRNA expression in the TCGA melanoma data, we selected MCL1, CD40LG, TNF, and TIGIT to examine their regulation by CD47 signaling in human Jurkat T lymphoblast cells." (PMID 36768931, 2023). "A study demonstrated increased STAT3 phosphorylation at Y705 in melanoma cell lines cultured in suspension conditions compared to adherent cells, driving upregulation of Bcl-2 and Mcl-1." (PMID 37181747, 2023). "The association of higher MCL1 with high CD47 and improved survival in melanomas suggests that this increased MCL1 is expressed by immune cells in the tumor microenvironment." (PMID 36768931, 2023). "We investigated the effect of three generations of mTOR kinase inhibitors alone and in combination with the MEK1/2 kinase inhibitor AS-703026 on the expression of pro-survival proteins: p-Bcl-2 (T56), Bcl-2, Bcl-xL, and Mcl-1 in MEWO melanoma cell line." (PMID 37097377, 2023). "For example, knockout of the anti-apoptotic gene MCL1 sensitized SKMEL2 melanoma cells to all 8 drugs." (PMID 37957169, 2023). "Activation of survival pathway and altered translation via persistent formation of eukaryotic translation initiation factor 4F (eIF4F) complex: Myeloid leukemia 1 (Mcl-1) overexpression was detected in D/T combination-resistant progressive melanoma biopsies." (PMID 37834284, 2023). "Bcl-xL and Mcl-1 protein levels predicted IS21 sensitivity in melanoma and ovarian cancer, respectively." (PMID 37460459, 2023). "STAT3 inhibition by an Src inhibitor leads to the downregulation of Mcl-1 gene expression in melanoma cells." (PMID 36080130, 2022). "In parental melanoma cells, BI-847325 induced apoptosis by decreasing the expression of MCL-1 at the transcriptional and translational levels." (PMID 35834029, 2022). "Interaction of Noxa with Mcl-1 has also been observed in melanoma cells treated with bortezomib, and in MDN and Jurkat cells where endogenous Noxa/Mcl-1 complexes were detected." (PMID 35207544, 2022). "Of note, removal of BFL-1 increased the death of M14 and SKMEL30 melanoma cells treated with a combination of the MCL-1 and the BCL-XL inhibitors." (PMID 35379799, 2022). "Here, we report the ability of PEL and EPI to cause apoptosis in melanoma cells through the contemporaneous increase in pro-apoptotic BAX mRNA expression and decrease in the anti-apoptotic BCL-2, BIRC-5, and MCL1 mRNA expression." (PMID 35877720, 2022). "We treated several melanoma-derived cell lines for 72 h with the MCL-1 inhibitor S63845, the BCL-XL inhibitor A1331852 or the BRAFV600E inhibitor PLX4032." (PMID 35379799, 2022). "This showed that CDK9i efficiently suppressed the levels of Mcl-1 and cFLIP not only in therapy-sensitive but, importantly, also in therapy-resistant melanoma cells." (PMID 34535764, 2022). "Recently, BFL-1 was shown to block the killing of some melanoma cells treated with a combination of MCL-1 and BCL-XL inhibitors." (PMID 35900226, 2022). "Here, we show that the cytotoxicity of AdV-TRAIL can be significantly enhanced in TRAIL-sensitive and TRAIL-resistant melanoma cells by silencing of Mcl-1." (PMID 34028599, 2021). "In conclusion, we show here that cytotoxicity of AdV-TRAIL can be enhanced in TRAIL-resistant and TRAIL-sensitive melanoma cells by co-silencing of the antiapoptotic Bcl-2 protein Mcl-1 by activation of apoptosis and necrosis." (PMID 34028599, 2021). "In a recent project, the groups showed that TRAIL resistance can be efficiently overcome in melanoma cells by inhibition of the antiapoptotic Bcl-2 protein Mcl-1." (PMID 34452286, 2021). "One such major mitochondrial adaptation is the overexpression of the MCL1 apoptosis regulator gene (MCL1), preventing apoptosis in melanoma cells and driving mitochondrial fusion to promote respiration." (PMID 34831420, 2021).
melanoma (continued). "This study also shows a clear dissociation between changes in Bcl-2 expression (downregulation) and Bcl-xL or Mcl-1 expression (upregulation) during progression of melanoma." (PMID 33803452, 2021). "These small regulatory RNAs can be easily inserted into the genome of AdV-TRAIL, in order to enable their melanoma cell-specific delivery and silencing of Mcl-1." (PMID 34028599, 2021). "Overexpression of myeloid cell leukemia-1 (MCL-1) serves as another possible mechanism of resistance to either vemurafenib or dabrafenib individually or in combination with trametinib in melanoma cells." (PMID 33807778, 2021). "It was reported that melanoma cells show higher basal expression of anti-apoptotic Bcl-2 proteins including MCL-1, Bcl-2 and Bcl-xL." (PMID 33523262, 2021). "Recently, we found that TRAIL resistance in melanoma cells can be overcome by inhibition of antiapoptotic Bcl-2 protein myeloid cell leukemia 1 (Mcl-1)." (PMID 34028599, 2021). "Regarding the strength of the increase in cytotoxicity induced in AdV-TRAIL-infected melanoma cells after silencing of Mcl-1, this was more pronounced in MeWo than in Mel-HO." (PMID 34028599, 2021). "In Melanoma, MCL-1 was defined as a target for downregulation by miR-339-3p, functioning through direct interaction with the 3′ UTR of MCL-1 mRNA." (PMID 34312371, 2021). "This indicates that inhibition of Mcl-1 has a greater impact on AdV-TRAIL activity when the melanoma cells are resistant to TRAIL." (PMID 34028599, 2021). "Recent studies have demonstrated dependence on MCL1 expression for the resistance of BRAFV600E mutant melanomas to apoptotic stimuli via the constitutive activation of the RAS/RAF/MEK/ERK signaling pathway." (PMID 34469478, 2021). "A similar synergy between BCL-XL and MCL-1 inhibition has also been observed in other types of solid tumor such as cervical cancer and melanoma." (PMID 33917026, 2021). "In melanoma, the relatively high proportion of MCL1 to BCL2L1 highlights its predominant role in preventing apoptosis." (PMID 34831420, 2021). "In contrast, the genetic knockdown of MCL-1 promoted the responsiveness of melanoma towards the BCL-XL inhibitor navitoclax." (PMID 34575429, 2021). "Our group and others have demonstrated that BCLXL and MCL1 are significant anti-apoptotic proteins responsible for melanoma cell survival." (PMID 34451846, 2021). "MCL-1 depletion significantly induced apoptosis in melanoma cells and resensitized mutant BRAF melanoma cells to anoikis compared with depletion of BCL-2 or BCL-xL." (PMID 33883020, 2021). "In a follow-up study in cooperation with Florian Kreppel (University Witten/Herdecke) the Berlin groups significantly enhanced AdV-TRAIL cytotoxicity in melanoma cells by Mcl-1 silencing." (PMID 34452286, 2021). "MIM1, a highly specific low-molecular-weight inhibitor of MCL-1, demonstrated promise in preclinical studies by inducing apoptosis in leukaemia, glioblastoma, and melanoma cell lines." (PMID 35008180, 2021). "Here, we show that cytotoxicity of the TRAIL-expressing oncolytic adenovirus AdV-TRAIL can be significantly improved in TRAIL-resistant and TRAIL-sensitive melanoma cell lines by silencing of the antiapoptotic Bcl-2 protein Mcl-1." (PMID 34028599, 2021). "Similar ABT-737-enhancing effects have also been reported upon Mcl1 inhibition in retinoblastoma-, melanoma-, breast-, prostate-, colon- and liver- cancer cells." (PMID 34753495, 2021). "In melanoma, the high expression of MCL1 protects cancer cells from apoptosis, making it a key target for lowering resistance to treatment." (PMID 34831420, 2021). "The involvement of Bcl-xL in melanoma progression was also proved by Liqing Zhuang’s group via immunohistology analysis of Bcl-xL and other anti-apoptotic proteins, as Bcl-2 and Mcl-1, in sections of benign nevi, primary melanoma and metastatic melanoma." (PMID 33803452, 2021).
melanoma (continued). "Previous studies revealed that BA had a potential to enhance the pro-apoptotic Bax and Mcl-1 levels in melanoma, neuroblastoma, glioblastoma and colorectal carcinoma cells." (PMID 34770786, 2021). "Aside from KRAS (colorectal cancer, amplified in 1% of TCGA cases), MCL1 (lung squamous carcinoma, 4.7%) and BRAF (melanoma, 4.1%) amplifications have also been implicated as oncogenic alterations in OncoKB." (PMID 34313788, 2021). "Overall, the findings presented here suggest that MCL1 inhibition plus AZA is a promising combination in melanoma treatment." (PMID 34451846, 2021). "We and others have demonstrated the efficacy of combining MCL1 inhibitors with other BH3 mimetics targeting multiple BCL2 family proteins to kill melanomas in vitro." (PMID 32513939, 2020). "The obtained results as well as accessible literature data indicate that antiapoptotic Mcl-1 protein seems to be crucial in melanoma cells death and survive." (PMID 31432325, 2020). "On the other hand, the melanoma cells with high level of Mcl-1 protein exhibited a resistance to ABT-737 treatment alone." (PMID 31432325, 2020). "The Mcl-1 protein level as a drug target in amelanotic melanoma cells was defined by Western blot analysis." (PMID 31432325, 2020). "Because BCL-xL levels were lower in melanoma, these results indicated that MCL-1 was predominant in melanoma cell lines and patient samples." (PMID 33308268, 2020). "T-96 inhibited cell proliferation and induced cell apoptosis through downregulating the expression of MCL1 in melanoma cells." (PMID 32382038, 2020). "The combination of BH3 mimetics targeting different anti-apoptotic proteins such as Bcl-2 and Mcl-1 or Bcl-xL and Mcl-1, has been reported to shown significant benefit for the treatment of melanoma." (PMID 32455818, 2020). "Previous studies have shown that the upregulation of MCL-1 is a major adaptive mechanism of melanoma cells to endoplasmic reticulum stress (ER stress)." (PMID 32586376, 2020). "We and others have shown that navitoclax plus MCL1 inhibitors can be effective to kill melanomas in vitro and in vivo; however, in our experience, the potential toxicity was higher than ABT-199 plus MCL1 inhibitors." (PMID 32764384, 2020). "Overexpression of MCL-1 have been reported in a wide range of human tumors, such as melanoma, non-small cell lung cancer, breast cancer, and ovarian cancer." (PMID 32586376, 2020). "We are the first to demonstrate the in vivo efficacy of targeting both MCL1 and BCLXL simultaneously in multiple mouse xenograft studies (both BRAF mutated and BRAF-WT melanoma lines)." (PMID 32513939, 2020). "Given the experimental evidence from our study, MIM1 – a selective Mcl-1 protein inhibitor, is a potent apoptosis inducer in the amelanotic melanoma cells." (PMID 31432325, 2020). "In both cellular and animal models of melanoma, both groups demonstrate that combined MCL-1 and RAF-MEK-ERK pathway inhibition yields striking therapeutic activity." (PMID 31988312, 2020). "In melanoma cell lines and tumors, they observed that the MCL-1:BCL-XL ratio is considerably higher than in colorectal, lung, and pancreatic tumors." (PMID 31988312, 2020). "So we focused on MCL1, which is amplified in many types of tumor, such as lung, breast, prostate, pancreatic, ovarian and cervical cancers, melanoma and leukemia, etc.." (PMID 33126914, 2020). "Similar to other malignancies, knockdown of MCL-1 sensitizes melanoma cells to various treatments, including BRAF or MEK inhibitors." (PMID 33308268, 2020). "This synergy was also observed in 3D spheroid cultures, where BH3-mimetic combinations targeting MCL-1 plus BCL-xL were most effective at killing melanoma cells." (PMID 33308268, 2020).